HMOX1 (heme oxygenase 1)
Diseases named in the same sentence as HMOX1 in open-access papers (continued):
Sharing a sentence is not in itself a finding about the gene and the disease.
Hepatic steatosis (45 papers, 2011 to 2026). Steatosis is a term used to denote lipid accumulation within hepatocytes. "Another study showed that MG inhibited hepatic steatosis-induced NLRP3 inflammasome activation through the restoration of autophagy to promote Heme Oxygenase-1 (HO-1) signalling." (PMID 36016562, 2022). "Activation of heme oxygenase-1 (HO-1) has beneficial effects to prevent fatty liver disease, which is most likely mediated by BVRA production of bilirubin." (PMID 32131495, 2020). "For example, molecular hydrogen activates nuclear factor 2-related factor 2 (NRF2) and its downstream antioxidant enzymes SOD1/2 and anti-oxidative stress protein heme oxygenase 1 (HO-1) to alleviate hypoxia reoxygenation injury and hepatic steatosis in hepatobiliary duct cells." (PMID 41194243, 2025). "Our findings identified SNPs significantly associated with disease risk, demonstrated altered expression of immune (IL-6, IL-8), antioxidant (SOD3, HMOX1), and lipogenic (ACACA, FASN) genes, and confirmed hepatic steatosis via ultrasonography." (PMID 41012815, 2025).
myocardial ischemia (45 papers, 2013 to 2026). A disorder of cardiac function caused by insufficient blood flow to the muscle tissue of the heart. "Eight genes (Aif1, Apoe, Arg1, Col1a1, Gpx7, Hmox1, Mmp14, and Sirpa) were significantly differentially expressed in the rat myocardial ischemia-reperfusion model." (PMID 36826575, 2023). "Overexpression of Hmox1 was found to alleviate cardiac ischemia/reperfusion injury and protect persistent heart failure from coronary ligation." (PMID 37424906, 2023). "Of note, allopurinol is reported to stabilize cardiac HIF-1α and heme oxygenase 1 protein expression, conferring synergistic cardioprotection against myocardial ischemia/reperfusion injury in diabetic rats." (PMID 36297636, 2022). "Additionally, a study found that a 1:1 ratio of dashes and HSYA positively influenced cardio protection against myocardial ischemia by modulating the protein kinase B (Akt)/nuclear factor erythroid 2-related factor 2 (Nrf2)/heme oxygenase-1 (HO-1) pathway." (PMID 40843199, 2025). "In a previous study, MSCs that overexpressed the heme oxygenase-1 (HO-1) gene and stained with super paramagnetic iron oxide (SPIO) significantly improved cardiac function compared with other MSCs after transplantation into a porcine myocardial ischemia/reperfusion model." (PMID 27447628, 2016).
preeclampsia (45 papers, 2010 to 2026). Preeclampsia is a hypertensive disorder of pregnancy that is characterized by new-onset hypertension with proteinuria presenting after 20 weeks of gestation, and depending on mild or severe forms may initially present with severe headache, visual disturbances, and hyperreflexia. "•Partial loss of heme oxygenase-1 under high soluble Flt-1 causes severe preeclampsia compared to high sFlt-1 alone." (PMID 33137710, 2021). "Human heme oxygenase-1 (Hmox1/HO-1) deficiency leads to severe and persistent endothelial damage, which is a hallmark of preeclampsia." (PMID 33137710, 2021). "Our laboratory demonstrated that preeclampsia is associated with high soluble fms-like tyrosine kinase 1 (sFlt-1) and low heme oxygenase-1 (HO1/Hmox1) expression." (PMID 33137710, 2021). "In humans, the variation in maternal and fetal microsatellites in the Hmox1 promoter is likely to predispose women to preeclampsia during pregnancy." (PMID 32660064, 2020). "Haploinsufficiency of Hmox1 (Hmox1+/−, single Hmox1 allele) has been associated with the dysregulation of angiogenic balance, leading to signs of fetal growth restriction and preeclampsia." (PMID 32660064, 2020). "Our results suggest that HMOX1 may be partially responsible for the loss of functionality in PE-DBMSCs and contribute significantly towards the pathophysiology of preeclampsia." (PMID 31964423, 2020). "Decreased expression of Hmox1 has also been associated with pregnancy disorders, such as recurrent miscarriages, intrauterine growth retardation, and preeclampsia." (PMID 24503248, 2014). "Heme oxygenase-1 (Hmox1/HO-1) is another protein that has protective effects versus oxidative stimuli and is altered in the placenta of pregnant women with preeclampsia." (PMID 34944543, 2021). "First trimester chorionic villous (fetal placental cells) sampling revealed a reduction in Hmox1 mRNA from women who subsequently went on to develop preeclampsia compared to normal pregnancy." (PMID 33137710, 2021). "Thus, we speculate that a down-regulation of Hif1α is caused by a deficiency in Hmox1, which could also occur in these trophoblast cells, and are well known for their role in SA remodeling, the failure of which is likely a contributing cause of preeclampsia." (PMID 32784053, 2020). "In preeclampsia, heme oxygenase-1 (Hmox1/HO-1) plays a protective role against the disease and is a negative regulator of sFlt-1." (PMID 32660064, 2020). "Heme oxygenase-1 (Hmox1/HO-1) exerts protective effects against oxidative stimuli and is compromised in the placenta of pregnant women with preeclampsia." (PMID 32660064, 2020). "Our laboratory had proposed that preeclampsia is a consicuence of high sFlt-1 and low heme oxygenase-1 and/or CSE1,22." (PMID 32978411, 2020). "Whilst robust up-regulation was observed in primary endothelial cells treated with all three classes of statins, only simvastatin increased heme-oxygenase 1 expression in placental explants obtained from women with preterm preeclampsia." (PMID 27207105, 2016). "While all statins up-regulated heme-oxygenase 1 in endothelial cells, only simvastatin up-regulated its expression in placenta from patients with preterm preeclampsia." (PMID 27207105, 2016). "The functional benefit of statins and Hmox1 induction in women with preeclampsia is valid not only because they inhibit sFlt-1 release, but also because statins and Hmox1 are associated with anti-apoptotic, anti-inflammatory, and anti-oxidant properties." (PMID 24503248, 2014). "In order to develop other therapies apart from statins to tackle preeclampsia, basic research is still needed to elucidate fully the role of Hmox1 and its metabolites." (PMID 24503248, 2014). "More importantly, statins induce Hmox1 and suppress the release of sFlt-1 and sEng; thus, statins and Hmox1 activators are potential novel therapeutic agents for treating preeclampsia." (PMID 24503248, 2014).
preeclampsia (continued). "Induction of Hmox1 or exposure to CO or bilirubin has been shown to inhibit the release of sFlt-1 and sEng in animal models of preeclampsia." (PMID 24503248, 2014). "Another study showed that the Hmox1 mRNA was decreased in the chorionic villous (fetal placental cells) sampling at just 11 weeks’ gestation in women who went on to develop preeclampsia compared with normal pregnancies." (PMID 24503248, 2014). "We previously proposed that the excess of free heme in Hmox1+/– animals contributes in part to gestational hypertension." (PMID 25628565, 2014). "In particular, pravastatin, a heme oxygenase-1 inducer with antioxidant properties, which has been investigated in clinical trials for the prevention of preeclampsia, might be an effective treatment for sSGA infants with oxidative damage." (PMID 34682470, 2021). "HMOX1 activation by statins and the following increase in HO-1 expression could diminish preeclampsia symptoms, allowing to extend the pregnancies." (PMID 33923744, 2021). "Here we assessed whether simvastatin and rosuvastatin regulate heme-oxygenase 1 expression in either endothelial cells or placental explants from women with preterm preeclampsia." (PMID 27207105, 2016). "Hmox1 is reduced prior to the increase in sFlt-1 as Hmox1 mRNA expression in the trophoblast is decreased in the first trimester in women who go on to develop preeclampsia." (PMID 24503248, 2014). "We have recently shown that rosiglitazone-induced PPAR-γ activation is able to ameliorate disease characteristics in the rat model of preeclampsia via its downstream target heme oxygenase-1 (HO-1), an enzyme which produces carbon monoxide (CO, a potent vasodilator) and bilirubin, an antioxidant." (PMID 24711815, 2014). "Therefore, the objective was to evaluate heme oxygenase-1 (HO-1) concentration in both plasma and urine samples from pregnant women before the development of preeclampsia and to identify a potential biomarker for preeclampsia development." (PMID 30363976, 2018). "Emerging therapeutic strategies targeting oxidative stress, inflammation, angiogenesis, and specific molecular pathways like the heme oxygenase-1/carbon monoxide (HO-1/CO) and cystathionine gamma-lyase/hydrogen sulfide (CSE/H2S) pathways show promise in mitigating preeclampsia’s effects." (PMID 39062815, 2024). "The decidual expression of the main “antioxidant protein” heme oxygenase 1 (HO-1) was significantly reduced in preeclampsia without FGR compared to preeclampsia with FGR." (PMID 35216082, 2022). "Interestingly, mice with homozygous deletion of heme oxygenase 1 (HO-1), one of the target genes of HIF-1α are infertile and heterozygous deletion results in preeclampsia like pregnancies with primarily absorption of HO-1–deficient fetuses." (PMID 33162999, 2020).
coronary artery disease (44 papers, 2009 to 2025). "Our data is potentially of great importance, due to the polymorphism of the HMOX1 promoter, which results in variations of HO-1 level in the population and impacts susceptibility for coronary artery disease." (PMID 33804563, 2021). "Plasma HMOX1 levels were associated with the severity of coronary heart disease, which was the highest in patients with AMI, followed by unstable angina pectoris and finally stable angina pectoris." (PMID 34685725, 2021). "A comprehensive meta-analysis concluded that the short GT genotype of the HMOX1 promoter was associated with decreased risk of coronary artery disease after controlling for biases due to age and sex matching, extent of coronary stenosis and ethnicity." (PMID 32993497, 2020). "Fewer GT repeats in HMOX1 promoter are also associated with a lower severity score in coronary artery disease." (PMID 32993497, 2020). "Numerous published studies have suggested that there is association between heme oxygenase-1 (HO-1) gene polymorphisms and coronary heart disease (CHD) or restenosis (RS) after percutaneous coronary intervention (PCI)." (PMID 27825138, 2016). "HMOX1 polymorphisms, in turn, may play a role in the development and progression of coronary heart disease and chronic kidney disease." (PMID 41155157, 2025). "Thus, the HMOX1 LL GTn and/or the -413A/T SNP genotypes could be utilized as possible risk markers for coronary heart disease, especially in men." (PMID 40826355, 2025). "Interestingly, although shorter (GT)n repeats typically enhance HMOX1 expression, some studies suggest that increased levels of HO-1 associated with longer (GT)n alleles may correlate with an elevated risk of coronary heart disease and CKD." (PMID 41155157, 2025). "There is no specific mechanism to explain this phenomenon, but some studies suggest that stress-induced increases in heme oxygenase-1 activity may be exacerbating the process of coronary artery disease." (PMID 36873413, 2023). "Among hypoxia-responsive genes identified in our in vitro hypoxic system, we also found potential cardiac biomarkers (BIRC5, ENG, HMOX1, VEGF, STC1, STC2, and SERPINE1) which they may have potential clinical value in the diagnosis and prognosis of coronary artery diseases." (PMID 34685725, 2021).
leukemia (43 papers, 2010 to 2025). A malignant (clonal) hematologic disorder, involving hematopoietic stem cells and characterized by the presence of primitive or atypical myeloid or lymphoid cells in the bone marrow and the blood. "HMOX1/HO-1 was 71.7-fold upregulated in CEM/ADR5000 leukemia cells and has been linked with doxorubicin and daunorubicin resistance in the present study." (PMID 34681275, 2021). "However, in contrast to leukemia cell lines, transcriptional response to oxidative stress was associated with induction of HMOX1, which was dependent on nuclear translocation of the transcription factor, Nrf2." (PMID 20618971, 2010). "Our findings revealed that HHT significantly increased the m6A modification levels of TNFRSF1B and HMOX1 mRNAs in leukemia cells." (PMID 41472850, 2025). "Taken together, our findings suggest that HHT enhances the interaction between EWSR1 and YTHDF2, thus inhibiting the recognition of the m6A‐modified target genes TNFRSF1B and HMOX1, ultimately leading to apoptosis in leukemia cells." (PMID 41472850, 2025). "A study reveals that Z-Ligustilide’s excessive activation of the nuclear factor erythroid 2-related factor 2 (Nrf2)/heme oxygenase-1 (HO-1) pathway is responsible for the selective onset of ferroptosis in leukemia cells." (PMID 40534879, 2025). "Such Nrf2-regulated cytoprotective genes include heme oxygenase-1 (HO-1), which has been shown to protect human leukemia cells from apoptotic signals." (PMID 24212776, 2011). "It has been reported that ROS induces HMOX1 in leukemia cells." (PMID 36775962, 2023). "In leukemia cells, elevation of HMOX1 induces Noxa to promote caspase-independent apoptosis." (PMID 36457077, 2022). "Furthermore, the inhibition of downstream targets of NRF2 such as heme oxygenase-1 (HO-1) have been shown to be able to decrease cell viability in leukaemia cells." (PMID 35582576, 2019). "HMOX1 upregulation has been identified in the adaphostin response in adherent cell lines, but not in hematopoietic cell line models, and it appears that adaphostin activates a different oxidative stress response in solid tumor models than in leukemia models." (PMID 20618971, 2010). "Therefore, determining the effect of common mutations of HMOX1 in MDS and leukemias could be of prognostic value." (PMID 36915102, 2023). "Consistent with the present study, EANT enhanced the mRNA expressions of NFE2L2, CAT, TXN, HMOX1, and NQO1 genes in leukemia cells in response to EANT-induced oxidative stress." (PMID 34573042, 2021). "Moreover, EK100 activated Nrf2/HO-1 (heme oxygenase-1) signaling in LPS-stimulated murine macrophage-like RAW 264.7 cells, murine microglial BV2 cells, and human monocytic leukemia THP-1 cells." (PMID 34573062, 2021). "Our research team had previously proved that overexpression of heme oxygenase-1 (one of Nrf2 target genes) promoted proliferation and increased resistance to Ara-C-induced apoptosis of AML cells in vitro and the leukemia’s progression of AML in vivo by activating the JNK/c-Jun signaling pathway." (PMID 33414469, 2021).
renal fibrosis (43 papers, 2010 to 2025). A final common manifestation of a wide variety of chronic kidney diseases characterized by glomerulosclerosis and tubulointerstitial fibrosis. "In a murine model of cyclosporine A-induced kidney injury, Hmox1 deficiency was associated with an increased mortality rate, renal fibrosis, inflammation (as indicated by elevated levels of the cytokine interleukin-6) and apoptosis." (PMID 39728801, 2024). "It has been shown that induction of heme oxygenase-1 (HO-1) by sEHI contributes to a decrease in renal fibrosis in diabetic SHR, producing increased EET levels, reduced renal collagen deposition, and fibronectin expression together with a reduction in glomerular TGF-β1 levels." (PMID 34639055, 2021). "Under the action of heme oxygenase-1 (HO-1), bone morphogenetic protein-7 (BMP-7), and hepatocyte growth factor (HGF), renal fibrosis can be blocked or even reversed." (PMID 31781634, 2019). "Several previously reported protective genes (hypoxia inducible factor 1, HIF-1α; heme oxygenase 1; HO-1, colony-stimulating factor 2, CSF-2; bone morphogenetic protein-7, BMP-7; and activin-like kinase 3; ALK3) against renal fibrosis progression after ischemia reperfusion were evaluated after IR." (PMID 34302012, 2021). "And the activation of Nrf2/ARE pathway can promote the expression of a range of downstream antioxidant enzymes, including heme oxygenase 1 (HO-1) and superoxide dismutase 1 (SOD-1), thereby reducing ROS level and resisting the renal fibrosis injury induced by oxidative stress." (PMID 33519483, 2020). "As oxidative stress plays a very important role in the development of renal fibrosis via EMT, we also analyzed the levels of key intracellular antioxidant machinery like nuclear factor (erythroid-derived 2)-like 2 (Nrf-2) and heme oxygenase-1 (HO-1) expression levels." (PMID 34067107, 2021).
heart failure (41 papers, 2009 to 2025). Inability of the heart to pump blood at an adequate rate to meet tissue metabolic requirements. "Expansion of these proinflammatory macrophage subsets in the infarcted hearts of Hmox1-deficient mice indicates their involvement in the heart failure progression." (PMID 28534119, 2017). "The causal role of oxidative stress in heart failure is highlighted by gene transfer studies of three primary antioxidant enzymes, thioredoxin, and heme oxygenase-1, and is further supported by gene therapy studies directed at correcting oxidative stress linked to metabolic risk factors." (PMID 34829874, 2021). "The causal role of oxidative stress in heart failure is also supported by gene transfer studies of the three primary antioxidant enzymes (SODs, catalase, and glutathione peroxidase), of thioredoxin, and of heme oxygenase-1." (PMID 34829874, 2021). "Forsythiaside A alleviated oxidative stress in mice with heart failure by activating the Nrf2/heme oxygenase-1 (HO-1) signaling pathway." (PMID 35958429, 2022). "This is due to the fact that in DOX-induced cardiac injury, the expression of inducible heme oxygenase Hmox1 is increased by Nrf2, which catalyzes heme degradation and promotes the release of free iron, giving rise to ferroptosis and ultimately heart failure." (PMID 35363601, 2022). "We finally demonstrated an important role of spleen in the post-MI mobilization of the proinflammatory Ly6Chi monocytes and heart failure progression in splenectomized Hmox1−/− mice." (PMID 28534119, 2017). "Opposite effect was observed in Hmox1-deficient mice where splenectomy was associated with significantly improved post-MI LV EF suggesting an important role of spleen in post-MI heart failure progression in Hmox1−/− mice." (PMID 28534119, 2017). "Then we took Angiotensin II Receptor (Type 1) (AGTR1), TNF-α and Heme oxygenase 1 (HMOX1) as an example to explain the potential synergistic mechanism of active components in SND for curing heart failure." (PMID 27095146, 2016). "However, transgenic mice that overexpressed Hmox1 were found to rapidly develop spontaneous heart failure within 1 year." (PMID 37424906, 2023). "Afterwards, however, the absence of Hmox1 is associated with adverse late LV remodeling and severe heart failure after MI." (PMID 28534119, 2017). "As HMOX1 was identified to be a target of active components of SND, these components may treat heart failure through opposing pathological left ventricular remodeling caused by HMOX1 induction." (PMID 27095146, 2016).